IL7R (interleukin 7 receptor)
Diseases named in the same sentence as IL7R in open-access papers (continued):
Sharing a sentence is not in itself a finding about the gene and the disease.
depression (4 papers, 2014 to 2024). "A view holds that as a homeostatic cytokine regulating T cells function, IL-7/IL-7R signaling pathway is involved in the cascade possibly contributing to the hypothesized depression-related lymphokine suppression." (PMID 39763672, 2024). "In addition, there are few studies on IL7R, IGLL5, and CD79A in depression." (PMID 36561317, 2022).
esophageal squamous cell carcinoma (4 papers, 2023 to 2025). Esophageal squamous cell carcinoma (ESCC) is a type of esophageal carcinoma (EC) that can affect any part of the esophagus, but is usually located in the upper or middle third. "In esophageal squamous cell carcinoma (ESCC), the interaction between cancer cells and macrophages induces IL-7R expression in cancer cells." (PMID 40313966, 2025).
glioma (4 papers, 2011 to 2025). A benign or malignant brain and spinal cord tumor that arises from glial cells (astrocytes, oligodendrocytes, ependymal cells). "The prognostic significance of IL7R expression in high-grade gliomas is supported by its association with reduced overall survival and its role in promoting tumor aggressiveness through immune evasion and microenvironment remodeling." (PMID 40165301, 2025). "MRI radiomics models have the potential to non-invasively predict IL7R levels in high-grade gliomas, which are closely associated with clinical outcomes." (PMID 40165301, 2025). "Recent studies have identified the expression of IL7R as a significant risk factor that affects the prognosis of patients diagnosed with high-grade gliomas (HGG)." (PMID 40165301, 2025). "Notably, the elevated expression of the LOX gene, along with a higher presence of M0 macrophages in the high-risk score group, supports the idea that IL7R may contribute to creating an immunosuppressive environment in gliomas." (PMID 40165301, 2025). "This underscores the need for further investigation into the therapeutic modulation of IL7R and its related pathways to enhance treatment outcomes for patients suffering from high-grade gliomas." (PMID 40165301, 2025). "Pathophysiological role of IL-7R in gliomas that survival of glioma patients starts to improve significantly after immunotherapy." (PMID 40165301, 2025). "In conclusion, our study underscores the promising role of radiomics in conjunction with machine learning algorithms for predicting IL7R expression in high-grade gliomas (HGG) and its implications for prognosis." (PMID 40165301, 2025). "This study represents a significant advancement in the non-invasive prediction of interleukin-7 receptor (IL7R) mRNA expression in high-grade gliomas (HGG) by enhanced magnetic resonance imaging (MRI)-based radiomics models." (PMID 40165301, 2025). "IL7R expression is a vital prognostic marker in high-grade gliomas." (PMID 40165301, 2025). "Further investigation into SOCS1’s expression in gliomas, using single-cell sequencing data from the CGGA and GEO databases, indicated that SOCS1 predominantly accumulates in tumor cells and T cells, exhibiting a similar expression pattern to immune markers such as CD8A and IL7R." (PMID 39654174, 2024).
Listeria infection (4 papers, 2012 to 2021). "Moreover, CD127 (also known as the IL-7R) expressing T cell subsets seemingly appear at early time points in response to Listeria monocytogenes infection which further falls in line with the notion that memory T cell development is rapid." (PMID 24171157, 2013).
liver cancer (4 papers, 2017 to 2025). An epithelial or non-epithelial malignant neoplasm that arises from the liver. "For example, Kong demonstrated the upregulation of Interleukin-7 receptor (IL-7R) could facilitate the proliferative and migratory activities of liver cancer cells through NF-κB and Notch1 pathways." (PMID 34544391, 2021). "DAPK1 expression was positively correlated with IRF2, IL7R, PCOLCE and ZBTB16, and negatively correlated with SLC16A3 in both liver cancer datasets." (PMID 28740751, 2017).
liver disease (4 papers, 2012 to 2025). "The aim of this study was to analyze the association between IL7R polymorphisms and severe liver disease in HCV/HIV coinfected patients." (PMID 26123260, 2015). "The aim of this study was to analyze the association between IL7R polymorphisms (rs6897932, rs987106, and rs3194051) and severe liver disease in HCV/HIV coinfected patients." (PMID 26123260, 2015). "The presence of IL7R polymorphisms seems to be related to severe liver disease in HIV/HCV coinfected patients, because patients with unfavorable IL7R genotypes (rs6897932 CC, rs987106 TT, and rs3194051AA) had a worse prognosis of CHC." (PMID 26123260, 2015). "According to what we have discussed until now, IL7R polymorphisms are related to increased odds of having severity of liver disease, possibly due to regulation of sCD127 levels." (PMID 26123260, 2015). "Mitigating the IL-7/IL-7R axis could enhance immune surveillance and provide a therapeutic approach to liver disease management." (PMID 40408005, 2025). "Targeting IL-7/IL-7R could offer a therapeutic approach for fibrosis-related liver diseases." (PMID 40408005, 2025). "Moreover, two genes (IL7R and LGALS3) are related to liver disease as they were manipulated in the literature of HCV and HCC." (PMID 22867264, 2012).
osteoporosis (4 papers, 2013 to 2022). A condition of reduced bone mass, with decreased cortical thickness and a decrease in the number and size of the trabeculae of cancellous bone (but normal chemical composition), resulting in increased fracture incidence. "In addition, IL-7/IL-7r can promote the RANKL-mediated osteoclast formation and bone resorption by activating the c-Fos/c-Jun pathway, as well as inducing bone loss in ovariectomized mice, a model of osteoporosis." (PMID 34206780, 2021).
parasitemia (4 papers, 2010 to 2026). "In line with the more rapid effect on parasitemia after adoptive transfer, there was a larger population of IL-7Rα− effector T cells (Teff) in the chronically infected mice (p = 0.038) compared with CQ-treated mice." (PMID 21124875, 2010).
acute leukemia (3 papers, 2016 to 2022). A clonal (malignant) hematopoietic disorder with an acute onset, affecting the bone marrow and the peripheral blood. "Overall, current information on the major contribution of normal IL-7R signaling to the onset, maintenance, and progression of acute leukemias opens a new and major area of research to develop and validate novel therapies focusing on the IL-7R pathway." (PMID 33081391, 2020). "Notable examples include the interleukin-7 receptor subunit alpha (IL7R), which is known to be involved in the occurrence and development of various forms of acute leukemias and solid tumors." (PMID 27150584, 2016).
Allergy (3 papers, 2013 to 2021). An allergy is an immune response or reaction to substances that are usually not harmful. "In addition, different studies have shown an association between genetic polymorphisms in the human IL-7Rα chain and TSLP genes with allergy, allergic rhinitis, and bronchial asthma further highlighting a possible link between these proteins and allergy." (PMID 24204367, 2013).
B-cell acute lymphoblastic leukemia (3 papers, 2018 to 2026). A neoplasm of lymphoblasts committed to the B-cell lineage, typically composed of small to medium-sized blast cells. "The inhibition of IL-7R signaling has been investigated across various malignancies, particularly hematologic cancers such as T-cell and B-cell acute lymphoblastic leukemia, and multiple therapeutic strategies are under development." (PMID 41596598, 2026).
cervical cancer (3 papers, 2013 to 2023). A primary or metastatic malignant neoplasm involving the cervix. "Cox regression analysis showed that IL7R can be used as an independent predictor of cervical cancer." (PMID 36890809, 2023). "Because TNF-α as an antitumor factor is negatively regulated by Lnc-IL7R, thus, we investigated its correlation in cervical cancer." (PMID 29720427, 2018). "The results showed that the expression of Lnc-IL7R was increased from normal tissues to neoplastic lesions and cervical cancer." (PMID 29720427, 2018). "The functions of Lnc-IL7R in vitro and in vivo were also assessed in cervical cancer cell lines Hela and SiHa." (PMID 29720427, 2018). "Since the Lnc-IL7R increased with the progression of cervical cancer, we next estimated the correlation between the expression of Lnc-IL7R and the clinicopathological characteristics of cervical patients." (PMID 29720427, 2018). "We here found that knockdown of Lnc-IL7R significantly impaired the cell vitalities of two cervical cancer cell lines HeLa and SiHa." (PMID 29720427, 2018). "But in the CIN samples, the high expression of Lnc-IL7R accounted for (57%) 20 in 35, which was further increased to (59%) 41 in 70 in cervical cancer." (PMID 29720427, 2018). "Functional experiments show that interference with IL7R expression can inhibit cervical cancer growth In vitro experiments show that Bcl-2 expression is reduced and caspase-3 expression is increased, which can inhibit cervical cancer growth by promoting apoptosis." (PMID 36890809, 2023). "The Lnc-IL7R-induced decreased expression of TNF-α might be conducive to the progression of cervical cancer." (PMID 29720427, 2018). "Moreover, knockdown of Lnc-IL7R by two different siRNAs in cervical cancer cell lines Hela and SiHa induced impaired cell vitality and caspase-3-dependent apoptosis in vitro." (PMID 29720427, 2018). "We reported that an oncogene Lnc-IL7R is increased during the development of cervical cancer, and could be an independent factor for the patients with cervical cancer." (PMID 29720427, 2018). "Knockdown of Lnc-IL7R inhibited the tumor growth in vivo, which could be a potential treatment for cervical cancer." (PMID 29720427, 2018). "Patients with high expression of Lnc-IL7R had poor prognosis with short overall survival (OS) time, and Cox regression analysis revealed that Lnc-IL7R could be independent prognostic factor for cervical cancer." (PMID 29720427, 2018). "In the present study, we investigated the potential clinical role of Lnc-IL7R in cervical cancer." (PMID 29720427, 2018). "We, here, investigated the clinical role of inflammation-related LncRNA-IL7R (Lnc-IL7R) in healthy cervical tissue (n=15), CIN 1/2/3 (n=35), cervical cancer (n=70), and clarified its function via knockdown in vitro and in vivo." (PMID 29720427, 2018). "The expression of Lnc-IL7R in normal, CIN, and cervical cancer samples, and its correlation to clinical characteristics were analyzed." (PMID 29720427, 2018). "In the present study, we found the clinical significance of Lnc-IL7R in cervical cancer, the expression of Lnc-IL7R was elevated in CIN tissues and cervical cancers, which predicted the poor clinical outcome of patients and could be an independent factor for cervical cancer." (PMID 29720427, 2018). "In the present study, an inflammation-related LncRNA, Lnc-IL7R, was up-regulated with the initiation and development of cervical cancer, which positively correlated to the tumor size, FIGO stage, and LNM, and could predict the poor prognosis of patients with cervical cancer." (PMID 29720427, 2018).
Chronic colitis (3 papers, 2012 to 2022). A chronic inflammatory disease of the large intestine (colon, cecum and rectum). "An increase in the infiltration of IL-7R-positive cells was reported in the lamina propria of TCRα−/− mice with chronic colitis." (PMID 27424033, 2016).
chronic hepatitis C (3 papers, 2021 to 2025). "In chronic hepatitis C the expression level of IL-7R correlated with the balance between the pro- and anti-apoptotic molecules Bim and Mcl-1 on HCV-specific CD8 T cells." (PMID 33802622, 2021).
dementia (3 papers, 2017 to 2023). Loss of intellectual abilities interfering with an individual's social and occupational functions. "Previous study has revealed that the downregulation of IL-7Rα in neurons and astrocytes could induce apoptosis of neurons in HIV-1-associated dementia." (PMID 28415697, 2017).
emphysema (3 papers, 2021 to 2025). "A feature importance analysis identified lnc-IL7R fold changes as the strongest predictor for emphysema classification (LAA% ≥15%), followed by CAT scores and BMI." (PMID 40361983, 2025). "Moreover, the feasibility of integrating the lnc-IL7R advanced biomarker for emphysema classification (LAA% ≥15%) was evaluated." (PMID 40361983, 2025). "Taken together, these findings suggest that lnc-IL7R could serve as a promising biomarker for classifying emphysema progression." (PMID 40361983, 2025). "Moreover, associative ellipsoid 3D visualization showed that increasing lnc-IL7R expression profile was associated with ameliorating COPD and %LAA-950insp-based emphysema severity." (PMID 35453536, 2022). "Correlative analyses further demonstrated that lnc-IL7R expression was anti-correlated with COPD severity (r = 0.59, p < 0.001), emphysema severity (r = 0.30, p = 0.002), and emphysema status (r = 0.35, p < 0.001)." (PMID 35453536, 2022). "Similarly, compared with the lnc-IL7R nonexpressors with severe emphysema, lnc-IL7R expressors, dependent on expression level, exhibited no, mild, or moderate emphysema." (PMID 35453536, 2022).
eosinophilia (3 papers, 2009 to 2021). "Total white blood cell count and eosinophilia in BAL fluid from OVA-treated RBP-jCKO;IL7rα-/- mice was indistinguishable from IL7rα-/- littermates." (PMID 19557146, 2009).
Miscarriage (3 papers, 2020 to 2023). A pregnancy that ends at a stage in which the fetus is incapable of surviving on its own, defined as the spontaneous loss of a fetus before the 22th week of pregnancy. "Due to the increase in the ratio of Th17/Treg cells, IL-2 has also been linked to preeclampsia, miscarriage, and the IL-7/IL-7R signaling pathway in fetal miscarriage." (PMID 38131979, 2023). "This might play an important role in pregnancy as IL-2 has been implicated to be upregulated in pre-eclampsia and miscarriage and IL-7/IL-7R signaling pathway in fetal miscarriage, due to the upregulation in the ratio of Th17/Treg cells." (PMID 32733490, 2020). "Interestingly, the IL-7/IL-7R pathway which was reported functional on up-regulating Th17 immunity is also able to downregulate Treg immunity in recurrent spontaneous abortion." (PMID 35757768, 2022).
myeloma (3 papers, 2012 to 2021). "This was not the case for Rag−IL-7− and Rag−IL-7R− mice (data not shown) suggesting that IL-7R signaling promotes nuclear translocation of β-catenin in Rag− IEC, similar to what was described for myeloma cells." (PMID 22384106, 2012).
Opportunistic infection (3 papers, 2013 to 2023). An infection that is caused by a pathogen that would generally not be able to cause an infection in a host with a normal immune system. "IL7R deficiency is a rare form of SCID that usually presents in the first months of life with severe and opportunistic infections, failure to thrive, and a high risk of mortality unless treated." (PMID 38082310, 2023). "IL-7 receptor α (IL-7Rα) deficiency is a rare form of SCID that usually presents in the first months of life with severe and opportunistic infections, failure to thrive and high risk of mortality unless treated." (PMID 31736942, 2019).
skin cancer (3 papers, 2025). "We identify that the same inflammatory myofibroblast phenotype (IL11+MMP1+CXCL8+IL7R+) can be observed in early human skin wounds, skin cancer and inflammatory skin diseases with scarring risk." (PMID 40993240, 2025). "Conversely, NK inactivation genes including Itga1 (Cd49a), Inpp4b, Tnfsf10, Il7r, and Cxcr6 dramatically decreased in skin tumors." (PMID 40282557, 2025).
T-cell immunodeficiency (3 papers, 2016 to 2025). A broad classification of disorders that affect the cell-mediated aspect of the immune response. "Cell-mediated immune defects have been partially explained by the lack of IL7Rα expression and IL-7 responsiveness due to hypermethylation of the IL7R promoter in SIOD T cells thus representing a hallmark of T-cell immunodeficiency in SIOD." (PMID 33203071, 2020). "Full or partial explanations for the vascular disease and T-cell immunodeficiency of SIOD patients are respectively decreased expression of elastin (ELN) in the aorta and of interleukin 7 receptor alpha chain (IL7R) in the T cells." (PMID 27816064, 2016).
abortion (2 papers, 2020 to 2024). the ending of pregnancy by removing a fetus or embryo before it can survive outside the uterus. "In abortion prone mice model, blocking of IL-7/IL-7R pathway by IL-7R antagonist significantly down-regulated Th17 immune responses while up-regulating Treg immunity in the decidua, and consequently, increased successful pregnancy outcome." (PMID 32973809, 2020).
Alzheimer disease (2 papers, 2022 to 2024). A progressive, neurodegenerative disease characterized by loss of function and death of nerve cells in several areas of the brain leading to loss of cognitive function such as memory and language. "Among them, IL-7R + neutrophils was a superior cell group in Alzheimer’s disease, GATA2 deficiency with susceptibility to MDSAML, breast ductal adenocarcinoma, diffuse gastric adenocarcinoma, and retinoblastoma." (PMID 38319415, 2024). "Since IL7Rα is expressed by the majority of ILC1s and hardly on NK cells in the adult, some IL7Rα+ NK cells detected in the CSF of Alzheimer’s disease are most likely ILC1s." (PMID 35185929, 2022).
Arthralgia (2 papers, 2020 to 2021). "A study evaluating clinically suspect arthralgia patients determined that IL-7R and IGF-1 were differentially expressed among individuals who did and did not progress to IA." (PMID 34071429, 2021).
autoimmune thyroid disease (2 papers, 2023 to 2024). Inflammatory disease of the thyroid gland due to autoimmune responses leading to lymphocytic infiltration of the gland. "This study aimed to assess the prevalence of selected single-nucleotide polymorphisms (SNPs) of Il7R, CD226, CAPSL, and CLEC16A genes in children with autoimmune thyroid diseases." (PMID 38612837, 2024). "The aim of this study was to assess the prevalence of selected single-nucleotide polymorphisms (SNPs) of Il7R, CD226, CAPSL, and CLEC16A genes in children and adolescents with autoimmune thyroid diseases, and in the control group." (PMID 38612837, 2024).
brain tumors (2 papers, 2025). "Gene profiling revealed that BV2 cells expressed higher levels of both M2‐associated genes (Maf, Selenop, P2ry14, Mrc1, Ctsc, and Cxcr4) and M1‐associated genes (Il7r, Atf3, and Gadd45g) compared to RAW264.7 cells, suggesting its multifaceted role in interaction with brain tumors." (PMID 40747560, 2025).
cardiomyopathy (2 papers, 2021 to 2025). A disease of the heart muscle or myocardium proper. "The gene expression of CXCL9, coding for MIG in monocytes, was also low in patients with cardiomyopathy, suggesting that IL-27/IL-27R and IL-7/IL-7R may be altered in other cell types." (PMID 34061845, 2021).
Chagas disease (2 papers, 2018 to 2021). A parasitic infection caused by Trypanosoma cruzi. "In chronic Chagas disease, Trypanosoma cruzi-specific T-cell function decreases over time, and alterations in the homeostatic IL-7/IL-7R axis are evident, consistent with a process of immune exhaustion." (PMID 34061845, 2021). "Impaired T-cell responses in chronic Chagas disease are specific for T. cruzi, but these alterations in the IL-7/IL-7R pathway are another example of how this chronic infection affects the general status of the host immune system." (PMID 30517089, 2018). "Taken together, the present study demonstrated that defective signaling and regulatory mechanisms in the IL-7/IL-7R axis during the chronic phase of Chagas disease may affect the maintenance of parasite-specific IFN-γ-producing cells." (PMID 30517089, 2018). "PBMCs from chronic Chagas disease patients and uninfected controls were examined for frequencies of T. cruzi-responsive IFN-γ-producing cells by ELISPOT and cellular expression and function of IL-7R using flow cytometry." (PMID 30517089, 2018).